TMPRSS2 (transmembrane serine protease 2)
Diseases named in the same sentence as TMPRSS2 in open-access papers (continued):
Sharing a sentence is not in itself a finding about the gene and the disease.
prostate carcinoma (continued). "Here, we showed for the first time that ERRα can transactivate the T:E fusion gene via its direct binding to TMPRSS2 promoter/enhancer in both AR-positive and -negative prostate cancer cells, with further potentiation by its coregulator PGC-1α." (PMID 30042415, 2018). "The results of our immunohistochemical analyses demonstrate that YB-1 has clinically relevant prognostic value, particularly in prostate cancers lacking the TMPRSS2:ERG fusion gene." (PMID 28515422, 2017). "Transcriptome analysis of VDR signaling in prostate cancer cells has been limited to microarray analysis and has not included a TMPRSS2:ERG positive cell line." (PMID 28591703, 2017). "The TMPRSS2-ERG fusion gene, comprising the androgen-responsive genes transmembrane protease, serine 2 (TMPRSS2), and estrogen-regulated gene (ERG), was observed in ~40–80 % of prostate cancers in 2005." (PMID 27730440, 2017). "The fusion event is an early, if not initiating, event in prostate cancer, implicating the TMPRSS2-positive prostate epithelial cell as the cancer cell of origin in fusion-positive prostate cancer." (PMID 27536883, 2016). "Despite gene rearrangements, such as the TMPRSS2-ERG genes fusion, recurrent mutations in the speckle-type POZ (SPOP) gene occur in up to 15% of prostate cancers making SPOP the most commonly affected gene by nonsynonymous point mutations in prostate cancer." (PMID 26863016, 2016). "This suggests that the likelihood of a TMPRSS2:ERG fusion event occurring may increase over time (i.e. with age), consistent with previous reports that prostate cancer incidence also increases with age." (PMID 27144529, 2016). "In addition, pharmacological inhibitors of Poly(ADP-Ribose) Polymerase inhibit TMPRSS2-ERG activity, and Luteolin up-regulates the prostate-derived Ets factor leading to inhibition of cell proliferation and cell invasion in prostate carcinoma cells." (PMID 27427904, 2016). "Based on the high frequency of TMPRSS2:ERG fusions and the potentially high impact on prostate cells by rendering ERG dependent genes androgen regulated, attempts were made to molecularly classify prostate cancer as “fusion-type” and “non fusion-type”." (PMID 27530104, 2016). "Prostate cancer shares many molecular and histologic similarities with luminal cells, including growth dependence on the androgen receptor (AR), as well as AR-dependent expression of seminal fluid proteases PSA and TMPRSS2." (PMID 27536883, 2016). "Among them, the most common fusion is TMPRSS2-ERG, which occurs in >50% of prostate cancers." (PMID 27200299, 2016). "For instance, some biomarkers such as PCA3 and TMPRSS2 are mRNAs not easily detected in body fluids, but are found in exosomes in prostate cancer." (PMID 26919248, 2016). "As a result, focused deep sequencing of TMPRSS2:ETS gene fusion negative Chinese prostate cancers identified high frequency and previously unrecognized genomic events in alternative pathways." (PMID 27551333, 2016). "Additionally, Topo II was also demonstrated to be responsible for gene fusion of TMPRSS2-ERG, one of the most common genomic alterations in prostate cancer." (PMID 26009876, 2015). "We observed similar effects at TMPRSS2; a gene that is a frequent target for chromosomal translocation in prostate cancer but did not meet fold cut-offs for DHT response in our analysis." (PMID 26332122, 2015). "Gene fusions involving the androgen-regulated serine protease TMPRSS2 and ERG, a member of the ETS family of transcription factors, occur in about 50 % of prostate cancers and result in strong AR-driven ERG protein overexpression and massive transcriptional changes." (PMID 26202067, 2015). "We tested the putative AR–HES6 and AR–ERG–HES1–HES6 transcriptional networks in AR-positive prostate cancer cells with and without TMPRSS2–ERG gene fusions (VCaP and LNCaP, respectively)." (PMID 25560400, 2015).
prostate carcinoma (continued). "This is suggested to be due to the fusion gene being a sign of early changes in the gland, but not always leading to malignancy, and naturally means that a positive TMPRSS2-ERG mRNA test result does not require the presence of a current prostate carcinoma." (PMID 26294063, 2015). "For example, the human prostate cancer VCaP cells are TMPRSS2-ERG positive with wild type AR, whereas human prostate cancer LNCaP cells are TMPRSS2-ERG negative with mutated AR." (PMID 24739220, 2014). "TMPRSS2-ERG fusion-positive prostate cancer cells show increased expression of several proliferation-related genes than do fusion-negative prostate cancer cells." (PMID 24739220, 2014). "c-myc is overexpressed in TMPRSS2-ERG fusion-positive prostate cancer cells as compared to normal tissue." (PMID 24739220, 2014). "However, treatment of prostate cancer cells with the analogue of 3,3'-diindolylmethane (BR-DIM) and curcumin inhibited AR/TMPRSS2-ERG/Wnt signaling." (PMID 24739220, 2014). "Likewise, some recent studies have also reported the presence of PCA3 and TMPRSS2-ERG fusion, two known prostate cancer biomarkers, in exosomes from urine samples of prostate cancer patients." (PMID 26317031, 2014). "TMPRSS2-ERG fusion gene is frequently present in human prostate cancer (50%) and it is not detected in normal prostate or BPH." (PMID 24877145, 2014). "Of these, overexpression of the ETS-related gene (ERG), resulting from the fusion of ERG coding sequences to the androgen-responsive TMPRSS2 gene, represents the most common subtype among ETS fusions, with a prevalence of approximately 50% in clinically localized prostate cancers." (PMID 25221645, 2014). "Because of the controversial prognostic utility of TMPRSS2:ERG fusion in prostate cancer, we employed the strategy of a three-marker FISH panel to detect well documented prostate cancer DNA aberrations, including TMPRSS2/ERG rearrangements, AR copy number gain, and PTEN deletion." (PMID 24098661, 2013). "The fusion of the TMPRSS2 gene with E-twenty six (ETS) family genes like ETV1, ERG and ETV4 occurs in up to 70% of all prostate cancers and is therefore a specific biomarker for prostate cancer diagnostics." (PMID 23341502, 2013). "Since their identification in 2005 by the pioneering studies of Arul Chinnayan, the TMPRSS2:ETS gene fusions have been the focus of intense investigations, as well as a point of contention with regards to its role in prostate cancer as an indicator for the aggressive phenotype." (PMID 24018887, 2013). "NDRG1 gene is also an ETS-family fusion partner in ERG-expressing prostate cancer but unlike TMPRSS2-ERG and SCL45A3-ERG fusions, prevalent in prostate cancers, the NDRG1-ERG fusion is thought to encode for a chimeric protein." (PMID 24386364, 2013). "Similarly, another fusion gene found in prostate cancer links the SLC45A3 fusion to the same Ets family of transcription factors, although the prevalence is lower than TMPRSS2-ERG fusions." (PMID 24349831, 2013). "A recently described gene fusion between TMPRSS2 and ETS family genes in prostate cancer may have clinical applications in diagnosis, prognosis and therapy." (PMID 25419445, 2012). "Recently the male sex hormone androgen has been demonstrated to promote the recruitment of androgen receptor (AR) and topoisomerase II beta (TOP2B) to genomic breakpoints induced at androgen responsive genes including TMPRSS2: ERG fusion, the most common fusion detected in prostate cancer." (PMID 23272087, 2012). "Androgen induces prostate cancer-specific translocations of TMPRSS2: ERG in prostate cancer cells but not in non-malignant prostate epithelial cells." (PMID 23272087, 2012).
prostate carcinoma (continued). "Notably, knockdown of the ATM gene expression in HPr-1AR cells can promote androgen-induced TMPRSS2: ERG rearrangement, a prostate-specific chromosome translocation frequently found in prostate cancer cells." (PMID 23272087, 2012). "SPINK1 is emerging as a biomarker of a molecular subtype of prostate cancer, in the absence of gene rearrangements/fusions such as TMPRSS2:ERG." (PMID 22641253, 2012). "Since TMPRSS2 is expressed in the prostate and regulated by androgens, its fusion to the transcriptional activators ETS gene products could result in driving prostate cancer development, and it appears that this is in fact the case." (PMID 22641253, 2012). "Since the discovery of a recurrent gene fusion between the androgen responsive gene TMPRSS2 (transmembrane protease, serine 2) and ERG (v-ets erythroblastosis virus E26 homolog (avian)) on chromosome 21, prostate cancers are molecularly divided into "fusion-positive" and "fusion-negative" cancers." (PMID 22142399, 2011). "However, the frequent fusion between TMPRSS2 and the ETS gene ERG showed that gene fusion is a highly relevant event in prostate cancer." (PMID 21298110, 2011). "To address this subject we performed genome-wide mRNA expression analysis on 6 non-malignant prostate samples and 24 prostate carcinomas with (n = 16) and without (n = 8) TMPRSS2-ERG fusion as determined by FISH." (PMID 21814574, 2011). "Chinnayian's group has identified androgen regulated prostate-specific serine protease (TMPRSS2) and ERG gene fusions, TMPRSS2-ERG, as the predominant molecular subtype of prostate cancer and demonstrated that TMPRSS2-ERG fusions help in distinguishing between PIN and prostate cancer." (PMID 24213111, 2011). "We have used a set of prostate cancer samples with and without the TMPRSS2-ERG fusion transcript to calibrate FusionSeq." (PMID 20964841, 2010). "Tomlins and colleagues (2005) identified recurrent gene fusions of TMPRSS2 to two ETS transcription factors, ERG and ETV1, and found evidence to suggest that these fusions may occur in the majority of prostate cancer cases." (PMID 18694509, 2008). "The TMPRSS2:ERG gene fusion is specific for prostate cancer, and the ability to identify this DNA rearrangement could be used as a screening test for prostate cancer in serum, prostatic fluid, or in urine." (PMID 18781147, 2008). "The T1/E4 variant is the most common of TMPRSS2:ERG gene fusions and is the best studied; it is not yet known if other variants are associated with prostate cancer prognosis to the same extent." (PMID 18781147, 2008). "This may change with recent suggestions that particular TMPRSS2-ERG fusion types are a predictor of aggressive disease and prostate cancer-specific mortality." (PMID 18694509, 2008). "Genes over-expressed in prostate cancer include AMACR, HPN, RDH11, and TMPRSS2." (PMID 16638148, 2006). "The TMPRSS2:ERG fusion process has also been described as involved in the regulation of long non-coding RNAs (lncRNAs), which are known to play an important role in the regulation of gene expression and to be deregulated in several types of cancer, including prostate cancer." (PMID 40332527, 2025). "In prostate cancer, androgen-activated nuclear AR functions as a classical transcription factor with relatively well-characterized transcriptional repertoire, including genes such as PSA, KLK2, FKBP5, and TMPRSS2, the alteration of which promotes prostate tumor aggressiveness." (PMID 38326303, 2024). "Recurrent gene fusions between TMPRSS2 (transmembrane protease serine 2) and the gene ERG, a member of the transcription factor erythroblastosis virus E26 transforming sequence family (ETS), are highly specific to PCa and can be found in up to 40-50% of prostate carcinomas." (PMID 39083067, 2024).
prostate carcinoma (continued). "The fusion of the androgen-regulated serine protease TMPRSS2 with the ETS family transcription factor ERG along with the inactivating rearrangements of the tumor suppressor gene phosphatase and tensin homolog (PTEN) are among the most common genetic alterations in prostate cancer." (PMID 37185705, 2023). "Furthermore, analysis of FOXP1 and TMPRSS2 expression in a human prostate cancer data set revealed a negative correlation." (PMID 36139541, 2022). "Therefore, in prostate cancers with the TMPRSS2-ERG fusion oncogene, activation of AR signaling upregulates the expression of this fusion oncoprotein, leading to enhanced proliferation and survival and prostate cancer cells." (PMID 35960413, 2022). "In urine-derived EVs (CD63-labeled vesicles), both TMPRSS2-ERG and a prostate cancer biomarker, Prostate Cancer Antigen (PCA-3) mRNA, were found, indicating that the mRNA composition of EVs is informative and may give prospective prostate cancer biomarkers." (PMID 36059497, 2022). "It is well established that TMPRSS2 is highly expressed in prostate epithelial cells, and the TMPRSS2-ERG [erythroblast transformation-specific transcription factor (ETS) -related gene, ERG] fusion gene is frequently expressed in benign prostatic hyperplasia and primary prostate cancer tissues." (PMID 34803967, 2021). "Furthermore, Wnt and β-catenin regulate EMT in prostate cancers without TMPRSS2-ERG family translocations." (PMID 34685470, 2021). "Dihydrotestosterone (DHT, AR activator) induces the expression of ACE2 and TMPRSS2 in activin-sensitive prostate cancer cells (LNCaP) and A549 non-small cell lung cancer cells, and GT0918 (a new generation of AR antagonists) can inhibit DHT-induced expression of ACE2 and TMPRSS2." (PMID 33396184, 2020). "In the present study, we selected TMPRSS2:ERG fusion as it represents the most common genomic alteration in prostate cancer, 11 chromosomal deletions because deletions are the next most prevalent genomic alterations in prostate cancer and tumor cell proliferation." (PMID 33195694, 2020). "About 50–70% of prostate carcinomas harbor common chromosomal rearrangements fusing one of the ETS transcription family genes (ERG, ETV1, ETV4 or FLI1) with androgen-regulated genes, most commonly TMPRSS2, leading to disruption of androgen receptor signaling via activation of EZH253." (PMID 32873863, 2020). "Additionally, the 5’ untranslated region of TMPRSS2 tends to fuse with E26 transformation-specific (ETS) family members through chromosome rearrangement, resulting in the overexpression of ETS genes and poor prognosis in prostate cancer." (PMID 31405024, 2019). "The observed comparable proportion of genomic repeat regions within the TMPRSS2 and ERG breakpoint cluster region to other mesenchymal tumors is an important prerequisite for the design of tumor-specific primers and probes for a highly sensitive therapy monitoring in prostate cancer patients." (PMID 31915468, 2019). "For instance, TMPRSS2 interacts with ERG and PTEN (see the example above) in the STRING version 10 protein-protein interaction (PPI) network; in fact all 3 genes co-operate to modulate the NOTCH signaling pathway in TMPRSS2-ERG–positive prostate cancer progression." (PMID 30978274, 2019). "Similarly, enzalutamide stimulated transcription of NR3C1 and SLC7A11 but not PSA or TMPRSS2, suggesting that enzalutamide-stimulated transcription is not limited to a single prostate cancer cell line." (PMID 31501863, 2019). "TMPRSS2-ERG or any ERG fusions were absent among African prostate cancers." (PMID 31366128, 2019).
prostate carcinoma (continued). "A study in 2005 demonstrated that the chromosome 21 genomic fusion event TMPRSS2-ERG, between the transmembrane protease serine 2 TMPRSS2 and the members of the ETS (erythroblast transformation-specific) transcription factor family ERG, is common in prostate cancer." (PMID 31275657, 2019). "First, TMPRSS2-ERG fusion was associated with T-stage at diagnosis (T3–4 vs. T1–2 OR: 1.40; 95% CI 1.33–1.48) and metastasis (M1 vs. M0 OR: 1.35; 95% CI 1.02–1.78) but not with biochemical recurrence or prostate cancer-specific mortality." (PMID 30459527, 2018). "Moreover, analysis of the VPD prostate cancer RNA-seq dataset using SCIF has identified 16 TMPRSS2-ERG fusion transcripts (rearrangements), 11 of which are novel (manuscript in preparation)." (PMID 28881586, 2017). "Whether a VDR agonist can reduce the growth of a prostate cancer cell line containing a TMPRSS2:ERG rearrangement in vivo has not been resolved." (PMID 28591703, 2017). "We further examined the activity of type 3 AR variants in prostate cancer Du145 and PC3 cells and breast cancer MDA-MB-453 and MFM-223 cells but found no androgen-independent activation of the PSA or TMPRSS2 enhancer reporter in these cell contexts (data not shown)." (PMID 28035996, 2016). "Given the key role of fusion protein TMPRSS2-ERG in regulation of IGF1R gene expression, we decided to evaluate next the hypothesis that IGF1R targeted therapy might be more effective in prostate cancer cells expressing the fusion protein in comparison to cells that do not express the chimera." (PMID 27285981, 2016). "To thoroughly evaluate the heterogeneity for MAP3K7 deletions and TMPRSS2:ERG fusion status and their interrelationship in prostate cancer, we took advantage of a newly developed heterogeneity tissue microarray (TMA) containing samples from 10 different tumor blocks of 189 large prostate cancers." (PMID 26684029, 2016). "However, there have been findings of TMPRSS2-ERG in the tissue of 6–8 % men with BPH but without history or suspicion of prostate cancer." (PMID 26294063, 2015). "Using the expression data of our series of prostate carcinomas subtyped for ETS rearrangements, we show that both PC3 and MDA-PCa-2b cells have co-overexpression of ETV1 and ETV4, both ETS in higher levels than those of ERG in VCaP cells, the in vitro model of the TMPRSS2-ERG rearrangement." (PMID 25595908, 2015). "Moreover, TMPRSS2 is androgen-regulated and forms a fusion gene with ETS TFs in prostate cancer." (PMID 25029565, 2014). "The impact of such SRs for prostate cancer biology is currently not understood, but a reasonable hypothesis is that they develop – like the TMPRSS2:ERG gene fusion – as a consequence of highly active androgen receptor (AR) signaling." (PMID 24684958, 2014). "Taken together, fusion-typing of a novel panel of TMPRSS2:ETS fusion markers allows detection of diverse fusion types in urine; multiple alternative fusion markers other than the common subtype I provide improved detection of prostate cancer in prebiopsy patients." (PMID 24133629, 2013). "Here we examine the accuracy of exoRNA to predict tissue expression of the prostate cancer-related gene fusion TMPRSS2:ERG (T:E) as well as determine the ability of biomarkers to differentiate prostate cancer-positive (BxPos) from prostate cancer-negative (BxNeg) patients." (PMID 26082317, 2013). "To date, this has not been possible in prostate cancer, although recent work suggests the imprinting of the TMPRSS2-ERG, PTEN, and androgen receptor configurational status may be suitable." (PMID 22096655, 2011). "However, a higher proportion of prostate cancer-specific deaths was observed in cases whose tumor was positive for the TMPRSS2-ERG fusion in comparison to those without, 7.9% vs. 4.4% respectively (p = 0.35)." (PMID 18694509, 2008).